FBXO9 (F-box protein 9)
Diseases named in the same sentence as FBXO9 in open-access papers (continued):
Sharing a sentence is not in itself a finding about the gene and the disease.
tumor (continued). "Further research is needed to investigate the precise mechanisms by which FBXO9 regulates EMT and the potential therapeutic implications of targeting FBXO9 and V-ATPase activity in tumor progression and metastasis." (PMID 38486234, 2024). "In contrast to FBXO9, whose expression is downregulated in AML patients compared to healthy controls and acting as a tumor suppressor in AML, FBXO22 is highly expressed in AML, especially MLLr AML patients." (PMID 36774506, 2023). "Mechanistically, as a direct upstream transcription factor, FBXO9 is regulated by zinc finger protein 143 (ZNF143) and accelerates tumor growth and metastasis by targeting the F-box and WD repeat domain containing 7 (FBXW7) for ubiquitination and degradation." (PMID 35847937, 2022). "Several F‐box containing proteins have been characterized either as tumor suppressors (FBXW8, FBXL3, FBXW8, FBXL3, FBXO1, FBXO4, and FBXO18) or as oncogenes (FBXO5, FBXO9, and SKP2)." (PMID 33822486, 2021). "To identify potential Fbxo9 substrates and protein alterations in AML, we performed quantitative MS on splenic tumor cells." (PMID 31684170, 2019). "Our analysis revealed a significant decrease in FBXO9 mRNA expression in tumor tissues compared to non-cancerous tissues (P < 0.0001)." (PMID 38486234, 2024). "Therefore, through our work, we uncover the mechanism by which FBXO9 exerts a tumor-promoting effect in HCC and propose a novel FBXO9-involved degradation mechanism of FBXW7." (PMID 35847937, 2022). "We observed an increase in differentially expressed proteasome components in tumors lacking Fbxo9, though some variation was seen between the different tumor samples." (PMID 31684170, 2019). "Although not significantly different, the kinetics of the cKit+ tumor population following Fbxo9 deletion differ, and this population expands at weeks six and nine." (PMID 31684170, 2019). "Transwell migration and tumor sphere formation assays demonstrated that the ATP6V1A-K393R mutant significantly enhanced cell migration and tumor sphere growth, which is consistent with observations of previous studies showing the augmented effects of FBXO9 depletion." (PMID 38486234, 2024). "Considering that FBXO9 expression is reduced in AML patients and that this reduction correlates with a negative prognosis, we generated a cKO mouse to provide a model for studying the role of FBXO9 in the tumor-initiating population, and in the development and progression of AML." (PMID 31684170, 2019).
cancer (7 papers, 2010 to 2026). A tumor composed of atypical neoplastic, often pleomorphic cells that invade other tissues. "The mechanisms underlying the effects of FBXO9 on cancer progression are poorly understood." (PMID 38486234, 2024). "Pharmacological inhibition of Akt signaling leads to YAP degradation in a GSK-3β/FBXO9-dependent manner, significantly enhancing chemosensitivity in cancer models." (PMID 40902979, 2025). "In another experiment, we introduced H1299 cancer cells with FBXO9 knockdown through tail vein injection." (PMID 38486234, 2024). "Overexpression of Fbxo9 significantly reduced cancer cell migration compared with the overexpression of Fbxl3, Fbxl5, or Fbxl8." (PMID 38486234, 2024). "To gain further insights, we generated cancer cell lines with inducible expression of V1A-23 aa (a peptide that inhibits ATP6V1A ubiquitination) by disrupting the interaction between FBXO9 and ATP6V1A." (PMID 38486234, 2024). "We hypothesized that that FBXO9 might regulate V-ATPase activity and cancer metastasis through V1 domain ubiquitination." (PMID 38486234, 2024). "Silencing FBXO9 in A549 cancer cells by siRNA transfection substantially increased the expression of active β-catenin (the primary effector of the canonical Wnt signaling pathway), C-Myc and cyclin D1 (both important downstream targets of this pathway) upon FBXO9 depletion." (PMID 38486234, 2024). "Previous studies have shown that FBXO9 protein could function as either a cancer suppressor or an oncogene, depending on different cancer types." (PMID 38136595, 2023). "In addition, FBXO9, but not UBD, was found to be downregulated in OV and positively correlated with DNA damage repair pathways, suggesting FBXO9 as a potential cancer suppressor, likely via facilitating DNA damage repair." (PMID 38136595, 2023). "Moreover, we found higher expression of FBXO9 in the cancer tissues of patients in the advanced pathological stages than in those in early pathological stages." (PMID 35847937, 2022). "We utilized a mass spectrometry (MS)-based approach, to identify proteins upregulated when Fbxo9 expression is lost in tumors and identified various proteins previously shown to participate in cancer-related mechanisms, such as metastasis, proliferation, invasion, and metabolism." (PMID 31684170, 2019). "Furthermore, FBXO9, one UbRG within this signature, is downregulated in OV patients and cell lines, associates with DNA damage repair activity, and impacts the survival and proliferation of cancer cell lines, suggesting a potential role of FBXO9 in tumorgenesis of OV." (PMID 38136595, 2023). "Thus, our results confirm that FBXO9 mediates the cancer-promoting effect of ZNF143 in HCC." (PMID 35847937, 2022). "We manipulated the expression of FBXO9 in HEK293T and cancer cells via gene overexpression and RNA interference to determine the implications of FBXO9-mediated ATP6V1A ubiquitination." (PMID 38486234, 2024). "In line with this idea, CRISPR KO data from the CCLE database revealed a similar CERES project score for FBXO9 as that of BRCA1/2, suggesting that OV cancer cells exhibit comparable dependency on FBXO9 as on BRCA1/2." (PMID 38136595, 2023). "In this sense, FBXO9 might mimic BRCA1 and BRCA2, the well-established cancer suppressors for OV that maintain genomic stability via facilitating DNA damage repair and are dysfunctional in a large portion of OV patients." (PMID 38136595, 2023).
degenerative disease (1 paper, 2022). "The possible association of FBXO9 and degenerative disease phenotypes and also the involvement in the development of neuronal disorders have been reported." (PMID 35041720, 2022).
hematological malignancies (1 paper, 2022). "F-box protein 9 (FBXO9) belongs to the F-box protein family and exhibits oncogenic properties in hematological malignancies." (PMID 35847937, 2022).
myopathy (1 paper, 2023). A disease of the muscle in which the muscle fibers do not function properly. "So far only Fbxo9, being upregulated in a hindlimb unloading model and the association of Fbxo30 in Nebulin-mediated myopathy are known." (PMID 36969608, 2023).
FBXO9 also shares sentences with these, for which no sentence is quoted: acute myeloid leukemia (2 papers); cardiac hypertrophy (1); diabetes (1); respiratory distress syndrome (1); Sepsis (1).